ARG1 (arginase 1)
Diseases named in the same sentence as ARG1 in open-access papers (continued):
Sharing a sentence is not in itself a finding about the gene and the disease.
COVID-19 (continued). "On the other hand, in a corticosteroid-exposed patient with severe COVID-19, there appeared to be a cytoplasmic staining pattern of arginase-1 as well as an increase in granule count." (PMID 39253969, 2024). "We identified the emergence of disease-specific subsets of neutrophils, including an increase in arginase-1 expression in severe COVID-19 that is retained into convalescence." (PMID 39253969, 2024). "The lowest number of the common DEGs was observed between COVID-19 and IS, including ARG1, ACSL1 and IQGAP1." (PMID 39469068, 2024). "An increased ratio of MDSCs to memory CD8 effector T cells was observed in patients with severe ARDS due to COVID-19 compared to moderate COVID-19 patients, and the COVID-19 severity is correlated directly with lymphopenia and enlarged ARG1 activity." (PMID 36851096, 2023). "In both cancer and COVID-19, their suppressive activity is mediated through the production of Arg1, IDO, TGF-β, and iNOS." (PMID 36851096, 2023). "In particular, the bioavailability of arginine is seriously compromised in COVID-19 patients and there is an upregulation of ARG1 that skews the metabolism of arginine away from the synthesis of NO." (PMID 35323682, 2022). "We constructed a 3-gene signature consisting of ARG1, GIMAP7, and RFX2 models for the assessment of COVID-19 severity and prognosis, and found that they are associated with neutrophils, T cells, and hematopoietic stem cells, respectively." (PMID 36352845, 2022). "Studies evaluating MDSC function showed that MDSCs from COVID-19 patients were correlated with Arg-1 activity." (PMID 35572540, 2022). "The up-rugualted of the arginase 1 (Arg1), enzyme that metabolizes arginine to ornithine and urea, was associated with higher virus load in the PBMC of COVID-19 patients." (PMID 35847976, 2022). "We and others found a decrease of plasma l-arginine during severe COVID-19 that correlated with the activities of Arg-1 and iNOS." (PMID 35572540, 2022). "Recent studies have shown that COVID-19 patients have reduced arginine levels and increased RNA expression of ARG1 in peripheral blood mononuclear cells." (PMID 36352845, 2022). "Together, these findings suggest that overexpression of ARG1 contributes to COVID-19-mediated immunopathology and vasculopathy." (PMID 35323682, 2022). "The relative expression analysis demonstrated that Arg1 was significantly up-regulated in COVID-19 patients compared to healthy individuals (p < 0.01)." (PMID 33806290, 2021). "First, our study showed that the expression of Arg1 was substantially up-regulated in the whole blood of COVID-19 patients." (PMID 33806290, 2021). "Furthermore, the Arg1 level might serve as a valuable diagnostic marker for COVID-19." (PMID 33806290, 2021). "The relative expression analysis demonstrated there were approximately 2.3 times increased Arg1 expression in the whole blood of COVID-19 patients." (PMID 33806290, 2021). "The current study aims to evaluate the expression of Arg1 as a marker in the whole blood of COVID-19 patients." (PMID 33806290, 2021). "In the current study, we show that Arg1 is substantially up-regulated in COVID-19 patients compared to healthy individuals." (PMID 33806290, 2021). "In support of this, serum concentrations of arginase-1 were reduced in patients with COVID-19." (PMID 39253969, 2024). "Thus, our finding of increased intracellular arginase-1 with escalating COVID-19 severity is likely driven both by the infection itself and by the exogenously administered corticosteroids." (PMID 39253969, 2024). "Critically, we identify a hitherto-unreported block in arginase-1 release in severe COVID-19." (PMID 39253969, 2024). "Thus, neutrophils from patients with severe COVID-19 probably inhibit T cell activation by means other than release of arginase-1, and the cells appear to have an inability to effectively release arginase-1." (PMID 39253969, 2024).
COVID-19 (continued). "We went on to quantify arginase-1 MFI fold-change against FMO in whole blood neutrophils, NDNs, and LDNs, in an expanded cohort, which verified the increase in intracellular neutrophil arginase-1 expression in COVID-19 and most notably in convalescent individuals." (PMID 39253969, 2024). "Given the increased arginase-1 expression, we went on to assess whether neutrophils from patients with COVID-19 possessed T cell–suppressive function by coculturing healthy anti-CD3ε– and anti-CD28–stimulated T cells with neutrophil supernatants." (PMID 39253969, 2024). "Herein, we spotted CD58, a nonclassical monocyte, such as CD274 (PD-L1) known inhibitor of T-cell activation along with Arginase 1 highly expressed in neutrophils in COVID-19 patients or CD24 involved in neutrophil degranulation with an increased expression of neutrophil function." (PMID 36806094, 2023). "Cocultures with M-MDSC had high levels of Arg1, the suppressive effect of M-MDSC on T cell proliferation was reduced by the addition of L-Arginine, and plasma levels of Arg-1 and IL-6 were elevated in COVID-19 patients, which increased with increasing severity of disease." (PMID 37545508, 2023). "Moreover, there is an increase in ARG1 expression with COVID-19 that shifts the metabolism of arginine away from the synthesis of NO towards the formation of ornithine, polyamines, and proline." (PMID 35323682, 2022). "COVID-19 group demonstrated significantly increased tissue immunoexpression of Arginase-1 and IL-4 (p = 0.002 and p < 0.0001, respectively) and increased number of Perforin-1+ (p = 0.009), CD4+ (p = 0.009), CD68+ (p = 0.013), CD138+ (p < 0.0001) cells in comparison to the H1N1 group." (PMID 36430210, 2022). "The inhibition of arginase-1 or supplementation of arginine in severe COVID-19 patients could be a treatment to restore depleted arginine and impaired T cell function." (PMID 35185933, 2022). "A potential concern with arginine replenishment therapies is that arginine may be channeled via maladaptive pathways (ARG1) to worsen immune and vascular cell dysfunction in COVID-19." (PMID 35323682, 2022). "Immunohistochemistry and immunofluorescence on the lung autopsy of patients who died due to COVID-19 showed the presence of large numbers of Arg-1-positive cells and a high expression of intracytoplasmic Arg-1 in CD66b+, confirming them to be Arg-1-positive PMN-MDSC-like cells." (PMID 35572540, 2022). "Therefore arginase 1 inhibition and/or arginine replenishment should be considered as an adjuvant to the prevention/treatment of COVID-19." (PMID 34341659, 2021). "In line with the single-cell study, signs of an interferon response were observed irrespective of disease severity (IFIT1, IFIT3), while only severe COVID-19 patients’ granulocytes featured expression of genes with suppressive functionality, such as ARG1 or CD274 (PD-L1)." (PMID 33441124, 2021). "In addition to these alterations in ISGs, both our data and theirs reveal an increase in markers that are associated with G-MDSC activation, including Arg1 and S100A12, indicating that activated Arg1+G-MDSC play a role in severe COVID-19." (PMID 34341659, 2021). "The idea of evaluating Arg1 in patients with severe COVID-19 came from our previous research in which we analyzed the GSE1739 microarray dataset, including the peripheral blood mononuclear cells (PBMCs) of 10 SARS-positive and the PBMCs of four healthy individuals." (PMID 33806290, 2021). "Therefore, quercetin may serve as a therapeutic target for modulating arginase 1 activity and treating COVID-19/AF." (PMID 36352845, 2022). "For instance, while reducing the correlation between DEGs including IL10, CXCL8, NFKB1, ARG1, and SOD2, new strong associations appeared between ELANE, DEFA4, AZU1, CTSG, and LCN2, with an overall tendency to higher relationships amid neutrophil-mediated immunity genes in COVID-19 patients." (PMID 35269470, 2022).
COVID-19 (continued). "Furthermore, large amount of ARG1+G-MDSC cells was found in the lungs of patients who died from COVID-19 complications, which might deplete L-arginine, leading to impaired T cell receptor and endothelial function." (PMID 36209203, 2022). "Therefore, arginase 1 inhibition and/or arginine supplementation may be important for the prevention/treatment of severe COVID-19 and AF." (PMID 36352845, 2022). "Therefore, inhibition of arginase-1 and/or replenishment of arginine may be important in preventing/treating severe COVID-19." (PMID 34341659, 2021). "Additionally, RELMα can be a marker of AAMs, and in combination with the observation of decreased Arg1 may suggest that these macrophages could be downstream of IL-13 signaling during COVID-19." (PMID 34185704, 2021). "Indeed, immunosuppressive monocytes that resemble M-MDSCs based on the expression of high levels of the arginase-1 (ARG1) enzyme were discovered during COVID-19 evolution, thus indicating a likely role for these cells in the progression to lymphopenia by actively inhibiting immune effectors." (PMID 34685679, 2021). "While ARG1 and ACSL1 were upregulated in both diseases, IQGAP1 was downregulated in COVID-19 but upregulated in IS." (PMID 39469068, 2024). "A study of dysregulated myeloid cell responses in COVID-19 revealed that presence of CD274 and ARG1 expressing dysfunctional mature neutrophils contributed to severe COVID-19 disease." (PMID 37026002, 2023). "S5, S6, and S7 cells exhibited relatively aged states that highly expressed CXCL4 and ARG1 but lower SELL, which accounted for the majority of aged neutrophils, while S7 cells also showed the highest TNF-α expression in both KD and severe COVID-19 patients." (PMID 36159873, 2022). "To further explore the functional and clinical value of ARG1, GIMAP7, and RFX2, we analyzed the Bonn cohort, which included peripheral blood scRNA-seq data from 19 control and 22 COVID-19 patients." (PMID 36352845, 2022). "We constructed a 3-gene signature consisting of ARG1, GIMAP7, and RFX2 for the assessment of COVID-19 severity and prognosis, and determined the cell-specific expression of these genes." (PMID 36352845, 2022). "PMN-MDSCs from COVID-19 patients were able to inhibit the SARS-CoV-2-specific IFN-γ production by T cells and expressed high levels of Arg-1, iNOS, and TGF-β messenger RNAs (mRNAs)." (PMID 35572540, 2022). "M-MDSCs isolated from COVID-19 patients suppressed T cell proliferation and IFN-gamma production partly via an arginase-1 (Arg-1) dependent mechanism." (PMID 34220859, 2021). "To gain further insight in COVID-19-induced immunesuppression, we profiled monocyte expression of PD-L1 (CD274), ARG1, and HLA-DR by flow cytometry." (PMID 33674591, 2021). "MDSC display abundant immune suppressive mechanisms including IL-10, TGF-β, Arg-1, IDO-1, ILT3, COX-2, PD1L, and others, all of which were clearly increased in COVID-19 patients in this study." (PMID 33692788, 2021). "In support of expansion of functional Mo-MDSC in severe COVID-19, it has been proposed that expanded Mo-MDSC isolated from COVID-19 patients suppressed T cell proliferation and IFN-γ production partly via an arginase-1–dependent mechanism." (PMID 33479167, 2021). "This may offer a mechanistic reason for the sequestration of arginase-1 inside neutrophils in patients with severe COVID-19, although we also demonstrated that dexamethasone reduces neutrophil degranulation of both MPO and arginase-1 directly." (PMID 39253969, 2024). "COVID-19 neutrophils suppress T cell proliferation independent of arginase-1 and display an inability to release arginase-1." (PMID 39253969, 2024). "A LASSO regression classification model composed of ARG1, GIMAP7, and RFX2 was constructed, which could be used to distinguish the severity of COVID-19." (PMID 36352845, 2022).
COVID-19 (continued). "Another neutrophil state that emerged with COVID-19 (and was absent in healthy controls) was an ARG1+ immature and immunosuppressive state with immunomodulatory properties." (PMID 34782790, 2022). "Large infiltrates by Arginase 1+ G-MDSC (Arg+G-MDSC), expressing NOX-1 and NOX-2 (important for production of reactive oxygen species) were found in the lungs of patients who died from COVID-19 complications." (PMID 34341659, 2021). "However, the exact expression of ELANE, ARG1, and CXCL1, as well as neutrophil counting in COVID-19 patients, should be investigated by further studies to shed further light on COVID-19 treatment." (PMID 32582303, 2020). "Additionally, none of the recruits with convalescent COVID-19 had received corticosteroids for at least 6 weeks but had markedly increased arginase-1 levels, indicating that there are COVID-19–specific factors at play over and above the corticosteroid effect." (PMID 39253969, 2024). "This enzyme is also reported to be involved in the inflammation of the lungs, and it could be hypothesized that the correlated expression of ELANE and ARG1 might deteriorate the hemorrhaging of the lungs in SARS-positive patients and, similarly, COVID-19 patients." (PMID 32582303, 2020).
lung fibrosis (34 papers, 2013 to 2025). "The results demonstrate that myeloid DNMT3B limits the development of pulmonary fibrosis by limiting M2 macrophage polarization potentially by methylation of the promoter of the gene encoding arginase 1 (Arg1)." (PMID 35725453, 2022). "Given the importance of macrophages in the development of pulmonary fibrosis and the role of DNMT3B in macrophage polarization, myeloid DNMT3B limits the development of pulmonary fibrosis by limiting M2 macrophage polarization potentially by methylation of the promoter of the gene encoding Arg1." (PMID 40358164, 2025). "However, a recent report has shown that bleomycin treatment in C/EBPζ−/− mice results in lung ECM deposition associated with an increased number of Arg1-positive macrophages (M2) that activate lung fibroblasts, indicating that C/EBPζ can inhibit M2 polarization to alleviate lung fibrosis." (PMID 36299447, 2022). "Nonetheless, in both species, we confirmed a P2RX4/IL-6/ARG1, myeloid-mesenchymal circuit that is functionally important in lung fibrosis." (PMID 40875483, 2025). "Numbers of Arg1+ macrophages were increased in murine lung fibrosis and localized in proximity to fibroblasts in areas of fibrosis." (PMID 40875483, 2025). "Crosstalk between myeloid cells and fibroblasts was found to increase ARG1 and hence levels of ornithine, which induced pathologic collagen expression in lung fibrosis." (PMID 40875483, 2025). "In a pulmonary fibrosis model, Western blot and RT-qPCR analysis found that expression of M2-labeled Arg1 in USP25-/- mice was significantly reduced compared to WT mice." (PMID 39781451, 2025). "It is reported that the interaction between TGF-β1 and arginase-1 contributes to lung fibrosis in mice." (PMID 40612681, 2025). "In conclusion, we show the dependence of lung fibrosis on ornithine deriving from myeloid ARG1 in mouse models and in functional studies of IPF lung." (PMID 40875483, 2025). "Taken together, these data indicate ARG1 determines the pathologic accumulation of collagen in lung fibrosis." (PMID 40875483, 2025). "A study have shown that depletion of macrophages suppresses the progress of pulmonary fibrosis, which is related to reduction of Arg1 expression, highlighting the detrimental effects of the M2 macrophages." (PMID 38789926, 2024). "In this study, the most significant finding was the downregulation of Arg1 in the RT+NA group inferring that NA targets macrophages to reduce Arg1 release and alleviate radiation-induced lung fibrosis in the later stages in mice." (PMID 39723218, 2024). "It has been reported that IL-9 expressing Th9 cells and IL-9 promotes pulmonary fibrosis in mice, coinciding with monocyte-derived alveolar macrophages (Mo-AMs) expressing Arg1 in the BLM-induced lung fibrosis model." (PMID 38162655, 2023). "Genes such as arginase 1 (ARG1), were shown to be dysregulated in the alveolar macrophages during PRRSV infections, and integrin subunit alpha 8 (ITGA8) has been implicated in lung fibrosis." (PMID 33187194, 2020). "It was reported that IL10, ARG1, and AKT1 were all associated with the macrophage activation and apoptosis in pulmonary fibrosis." (PMID 31105564, 2019). "Interestingly, Arg1, C3, and Ccl17 are all genes considered to be biomarkers of alternatively activated macrophages, a cell type that requires Th2-regulated cytokines for its differentiation, and that also have been implicated in the progression of pulmonary fibrosis." (PMID 27169501, 2016). "For example, Arginase-1 (Arg1) has been used in animal models as the molecular marker for SSc-Related Progressive Lung Fibrosis." (PMID 26444860, 2015). "Fizz-1 was initially identified in models of murine asthmatic models and has been implicated in mediating the deposition of extracellular matrix in an animal model of lung fibrosis and, thus, participating in wound healing and tissue remodeling like Arg-1." (PMID 23991225, 2013).